CCND1 (cyclin D1)
Diseases named in the same sentence as CCND1 in open-access papers (continued):
Sharing a sentence is not in itself a finding about the gene and the disease.
melanoma (continued). "Suppression of miR-106b in A375 and Hs294t human melanoma cells caused inhibition of cyclin D1, D2 and E, and reduction in the expression levels of CDK2, CDK4 and CDK6 proteins in both cell lines." (PMID 25361006, 2014). "Subtype 1.4 is associated with aberrations in both the MAPK and CDK pathways, specifically activation of BRAF and over-expression of CCND1/Cyclin D. The CDK pathway has been suggested to contribute to metastasis of melanoma with BRAF mutations." (PMID 21479172, 2011). "Progressive increase in expression of cyclin D1 and pRb is associated with progression to melanoma cells; however, cyclin D1 and pRb show relative decrease in thick melanoma and metastatic melanoma." (PMID 20936153, 2010). "Several proteins have been shown to be targeted by the BRAF/MEK/ERK signalling pathway in distinct tumours models (melanoma, colorectal and thyroid carcinomas); those proteins include cyclin D1 and p27Kip1, implicated in cell cycle regulation." (PMID 19878585, 2009). "However, some published studies showed that both metformin (1 mM) and binimetinib (2 μM) caused a decrease in cyclin D1 expression in melanoma cells after 24 h." (PMID 41373567, 2025). "In addition, genes implicated in cell cycle progression, including cyclin D1 and cyclin E, are commonly amplified in melanoma." (PMID 38339136, 2024). "Overviewing all of our data together, pterostilbene demonstrates a potent anticancer influence against melanoma cells in vitro thought cyclin D1, p21, and caspase 3, causing cell cycle arrest as well as both caspase-dependent and caspase-independent cell death." (PMID 36674631, 2023). "CCND1 is usually up-regulated in melanomas and associated with primary tumor growth and expansion." (PMID 37174717, 2023). "CCND1 amplifications in melanoma are associated with resistance to checkpoint inhibitors." (PMID 35993275, 2022). "In mantle cell lymphoma and multiple myeloma, the majority of CCND1 mutations occurred within the amino terminal domain of cyclin D1, while in endometrial adenocarcinomas, and less frequently in colorectal carcinoma and melanoma, CCND1 mutations centered on the carboxy terminal domain." (PMID 29969496, 2018). "Together, these results indicate that the Gö6976-induced E-cadherin expression, membrane translocation of β-catenin and loss of cyclin D1 expression correlate with a decreased anchorage-independent growth and migration capacity of the M2 metastatic melanoma cells." (PMID 28056869, 2017). "High expression of the surface protein CD36, the transcription factors Early Growth Response Protein 1, Cyclin D1, and L-Myc and of the enzyme ChAT have been linked to tumor progression, poor survival and increased metastasis in several cancers, including melanoma and recently also in lymphoma." (PMID 36831273, 2023). "However, there are also genome-wide copy number alterations in melanoma: amplification affects the melanoma oncogenes, as well as CCND1 (cyclin D1) and MITF, while loss of heterozygosity (LOH) or complete loss may affect CDKN2A (p16) and PTEN." (PMID 35628196, 2022). "MEK inhibitors can activate phospho‐ERK (pERK) in the NRAS‐mutant melanoma cell lines, and activation of pERK leads to cyclin‐D1 expression and therapeutic escape." (PMID 41492362, 2026). "Both MAPK and PI3K pathway can upregulate CCND1, and cell cycle regulation is a hallmark of malignant tumors including NRAS‐mutant melanoma." (PMID 41492362, 2026). "A defining feature of BRAF-mutant melanoma is the upregulation of proliferation-associated genes, such as MYC, CCND1, and E2F1, which synergistically fuel the unchecked growth of melanoma cells." (PMID 40872623, 2025). "In order to confirm the transition of the melanoma cells to a senescent state under vemurafenib treatment, we analysed the expression and evaluated the mRNA levels of cyclin D1 (CCND1) and RBL1." (PMID 40636307, 2025).
melanoma (continued). "For P1, clusters enriched in ER lumen-associated proteins (CIP2A, OSMR, WWTR1), inflammasome-related proteins, and melanoma-specific proteins (CCND1, MITF, MLANA, NOTCH1) were notable." (PMID 40669378, 2025). "In B16F10 melanoma cells, palbociclib decreased protein levels of cyclin A2 but increased cyclin D1 and cyclin E1 protein levels." (PMID 40904502, 2025). "An elevated CCND1 copy number is defining characteristic of malignant melanoma and correlates with poor prognosis in melanoma patients." (PMID 39948552, 2025). "Cell proliferation is regulated by cell cycle whose progression from the G1 to the S phase is mediated by cyclins, as cyclin D1, which is overexpressed in different tumors and also in melanoma." (PMID 40868208, 2025). "The results of our investigations verified that c-Myc and cyclin D1 expression can be decreased in BRAF mutant melanoma cells by inhibiting the MAPK pathway." (PMID 39944829, 2025). "Functionally, knocking down GAS5 in melanoma cells accelerates G1/S progression through increases in cyclin D1, CDK4, and p27; boosts viability; and blunts apoptosis via increased expression of Bcl-2." (PMID 41463281, 2025). "In this study, we aimed to evaluate the anti-cancer efficacy of ArcA as a cyclin D1/CDK4 inhibitor in metastatic melanoma cells, specifically using highly metastatic derivatives that had metastasized to the lung and brain." (PMID 39948552, 2025). "BNCT rarely causes morphological changes in normal melanocytes, whereas melanoma cells treated with BNCT display marked changes in their ECM and a significant decrease in cyclin D1 levels." (PMID 41477294, 2025). "Correspondingly, our previous studies utilizing single-cell RNA sequencing revealed a progressive upregulation of cyclin D1 in metastatic melanoma cells that had spread to the lung and brain compared to their matched primary melanoma cells." (PMID 39948552, 2025). "Treatment with 1,25- D3 of RIPK4.KO cells, compared to their wild-type counterparts, significantly reduced proliferation in 2D and 3D culture (MTT or ATP assay) and decreased p-p65 and cyclin D1 levels in melanoma cells." (PMID 40490050, 2025). "According to the RT-PCR results, CCNA2 and CCNB1 expression levels decreased across all canine melanoma cell lines, whereas CCND1 expression was notably increased." (PMID 40642276, 2025). "Other experimental studies have demonstrated that metformin increases CCND1 expression in A2058 melanoma cells, which is consistent with our findings in both cell lines." (PMID 41373567, 2025). "The four-probe FISH assay targeting 6p25 (RREB1), 6q23 (MYB), CEP6 (centromere 6), and 11q13 (CCND1) helps to differentiate histologically unequivocal melanomas from benign nevi." (PMID 38247727, 2024). "For the genes with a lower expression in the Q4 tumours, the relevant pathways were hsa05218, melanoma; hsa04014, Ras signalling pathway; hsa05226, Gastric cancer, with CCND1 and FGFs highlighted in these pathways." (PMID 38612869, 2024). "Since BCL3ANT interfered with the activity of cyclin D1, we examined melanoma cell proliferation by using two different cell lines." (PMID 38238702, 2024). "After establishing that BCL3ANT interferes with the expression of cyclin D1, we wanted to examine the effect of Bcl-3 inhibition in melanoma cells." (PMID 38238702, 2024). "Consistent with increased PCNA and TOP2 expression, cyclin D1 protein levels were also markedly enhanced after induction of CD133 expression in both melanoma cell lines." (PMID 38727313, 2024). "Common aberrations, which have influence on melanoma development, include CDKN2A (p16 coding gene) mutations and deletions as well as CDK4/6 genes and CCND1 (cyclin D1 coding gene) amplification." (PMID 39598629, 2024). "After ASNS knockout, the cyclin‐dependent kinase (CDK4), cyclin‐dependent kinase (CDK6), and cyclin D1 significantly downregulated in melanoma cells, which decreased cell proliferation." (PMID 39210809, 2024).
melanoma (continued). "Taken together, these data suggest that treatment of melanoma cells with BCL3ANT reduces cell proliferation by blocking the G1-to-S cell cycle transition via inhibition of cyclin D1 expression and limits the growth of the cells in vivo." (PMID 38238702, 2024). "The expression of cyclin D1 and cyclin E, which regulate cell proliferation, is deregulated in many cancers, including melanoma." (PMID 38339136, 2024). "We identified a small molecule that inhibited cyclin D1 expression and proliferation in melanoma cells and suppressed tumor growth in animals." (PMID 38238702, 2024). "Previously, we demonstrated that HPF can inhibit melanoma cell proliferation by impairing retinoblastoma protein phosphorylation (pRB) and the expression of other cell cycle regulatory proteins, including cyclin D1." (PMID 37507910, 2023). "We conclude that elevated p21 expression is required to inhibit NER during S phase in cyclin D1 (T286A)–overexpressing melanoma cells." (PMID 37301510, 2023). "At the gene level, CCND1 was the most common high‐level amplification, found in 20 samples (5% of all melanomas)." (PMID 36219477, 2023). "T cell responses were induced to other melanoma antigens, including hTERT, gp100, and Cyclin D1 in some patients." (PMID 38022659, 2023). "Acral melanoma is another form of melanoma common in East Eurasian with a higher degree of chromosomal aberrations, including an increased cyclin D1 (CCND1) copy number." (PMID 37658191, 2023). "Fluorescence in-situ hybridization (FISH) utilizing probes for genes RREB1 (6p25), cMYC (8q24), CDKN2A (p16)/CEN9, and CCND1 (11q13) has been shown to be sensitive and specific for differentiating Spitz nevi from spitzoid appearing melanoma." (PMID 37877026, 2023). "NF-κB upregulated Myc and cycle regulator proteins, cyclin D1, and cyclin-dependent kinase 2, which further promoted melanoma growth." (PMID 37503344, 2023). "Exposure of amelanotic C32 melanoma cells to pterostilbene at all concentrations for 12 h resulted in down-expression of CCND1 mRNA compared to untreated cells." (PMID 36674631, 2023). "While there were no clear objective responses to VSV-IFNβ-TYRP1, dose-dependent immunogenicity to melanoma antigens was seen, both to virus-encoded TYRP1 and other melanoma antigens (gp100, hTERT, and cyclin D1), suggesting epitope spreading." (PMID 38022659, 2023). "In summary, we analyzed data from three different cohorts of patients with melanoma to explore CCND1 amplification as a distinct genomic subtype." (PMID 35844619, 2022). "To investigate the relationship between CCND1 amplification and CCND1 mRNA expression, we stratified the 367 melanoma samples from TCGA based on CCND1 amplification levels." (PMID 35844619, 2022). "We have previously reported findings from a sample of melanoma tumors that revealed significant enrichment for cyclin D1 (CCND1) amplification in patients with a Triple-WT genomic classification and these patients had a lower response rate to ICIs." (PMID 35844619, 2022). "This suggests that CCND1 amplification is mutually exclusive with BRAF, RAS, and NF1 mutations, which account for the three most common mutant genes observed in melanoma." (PMID 35844619, 2022). "To further verify signaling pathways activated in melanoma with CCND1 amplification, we performed a GSEA comparing the CCND1 Amplification and CCND1 Neutral groups using data from TCGA." (PMID 35844619, 2022).
melanoma (continued). "We found that RSK2 promoted melanoma cell proliferation and vemurafenib resistance by upregulating cyclin D1 expression." (PMID 36210843, 2022). "In agreement with the in vivo data, treatment of TRA alone or together with CQ decreased pERK and Cyclin D1 expression in B16, A2058 and A375 melanoma cells." (PMID 35847840, 2022). "Our study discovered that cyclin D1 expression was upregulated in vemurafenib-resistant melanoma cells, accompanied by the increase of RSK2." (PMID 36210843, 2022). "Here, we confirmed the mechanism of RSK2 in promoting melanoma cell proliferation was to elevate cyclin D1 transcription." (PMID 36210843, 2022). "In order to further investigate the immune microenvironment of CCND1 amplification, we developed a murine model of melanoma with CCND1 amplification." (PMID 35844619, 2022). "Inhibition of cyclin D1 restored the sensitivity of the vemurafenib-resistant melanoma cells to vemurafenib mediated by RSK2." (PMID 36210843, 2022). "CCND1 was selected to compare with the cell cycle assay due to our previous investigation of melanoma inhibition by resveratrol." (PMID 36452505, 2022). "Mechanistically, RSK2 enhances the phosphorylation of FOXO1 by interacting with FOXO1 and promoting its subsequent degradation, leading to upregulation of cyclin D1 in melanoma cells." (PMID 36210843, 2022). "We assigned each melanoma sample a CCND1 amplification level score, defined as: Neutral group (n=191), Amplification group (+1; n=46), and High Amplification group (+2; n=23)." (PMID 35844619, 2022). "An improved understanding of the microenvironment of melanoma harboring CCND1 amplification will support the development of new and effective therapies." (PMID 35844619, 2022). "Among the 302 Chinese melanoma patients whose tumor tissue underwent targeted sequencing with a 1021-gene panel we found CCND1 amplification in 7.62% of cases (23/302)." (PMID 35844619, 2022). "RAS is the second major mutant gene in melanoma and the co-occurrence frequency with CCND1 amplification was 1.32% (4/302), 1.63% (6/367), and 0.86% (3/350) among the Geneplus, TCGA, and MSKCC cohorts, respectively." (PMID 35844619, 2022). "Taken together, our results revealed that FOXO1 is a novel RSK2 substrate and discovered a new RSK2–FOXO1–cyclin D1 cascade involved in melanoma cell proliferation." (PMID 36210843, 2022). "In contrast, the MSKCC cohort showed that CCND1 amplification was an unfavorable prognostic factor for patients with melanoma, especially for patients who received ICIs and had a high tumor mutation burden (TMB)." (PMID 35844619, 2022). "Next, we used CIBERSORT to evaluate the immune infiltration of 22 immune cell subsets whose expression was up-regulated or down-regulated in melanoma with CCND1 amplification." (PMID 35844619, 2022). "Given the unique properties and complexity of melanoma, it is essential to explore the CCND1 amplification landscape specific to melanoma and identify unique pathopoiesis mechanisms." (PMID 35844619, 2022). "Melanomas with BRAF class 1 mutations harbored fewer amplifications of GAB2 (FDR = 0.099), CCND1, and PAK1 (both FDR = 0.18)." (PMID 35706047, 2022). "Notch1 deficiency sensitizes melanoma cells to stress-induced cell death and repress proliferation ability in part by inhibiting CCND1, resulting in decreasing in melanoma growth." (PMID 35585935, 2022). "Together, we have uncovered a new mechanism RSK2-mediated phosphorylation and stabilization of FOXO1, thereby increasing cyclin D1 expression, is involved in promotion of melanoma cell proliferation." (PMID 36210843, 2022). "Our results reveal that RSK2 not only promotes melanoma cell proliferation, but also mediates vemurafenib resistance through the upregulation of cyclin D1 mediated by accelerating the degradation of FOXO1 by phosphorylation." (PMID 36210843, 2022). "Together, these results indicated that RSK2 increases cyclin D1 by promoting FOXO1 degradation in melanoma cells." (PMID 36210843, 2022).
melanoma (continued). "As expected, melanoma patients with CCND1 amplification showed significantly shorter OS than the CCND1 neutral group (P=0.0029)." (PMID 35844619, 2022). "We confirmed that CCND1 amplification is an unfavorable prognostic factor for patients with melanoma, especially for patients receiving ICIs and who were simultaneously harboring high TMB." (PMID 35844619, 2022). "Although melanoma is generally regarded as an immunogenic cancer that will respond to immune checkpoint inhibitors (ICIs), melanomas with CCND1 amplification respond poorly to these therapies." (PMID 35844619, 2022). "Cyclin D1 regarded as oncogenic protein to promote cell proliferation has been reported to be upregulated in various malignancies including melanoma." (PMID 35484605, 2022). "For example, acral and mucosal melanomas have fewer BRAF mutations but more frequent KIT mutations, amplifications of CCND1, CDK4, and MDM2, and deletion of SPRED1." (PMID 35706047, 2022). "Variants highly associated with melanoma were also found in three other regions: oculocutaneous albinism 2 (OCA2, chr15:27670078–28337214), E-cadherin (CDH1, chr16:68528729–68923897) and cyclin D1 (CCND1, chr11:69210414–69803433)." (PMID 35357426, 2022). "Overexpression of cyclin D1 has also been found in up to 62% of primary melanomas compared with melanocytic naevi." (PMID 36210843, 2022). "Our results showed that knockdown of Piezo1 suppressed the viability of melanoma cells and decreased the expression of Cyclin D1 and CDK2." (PMID 36112948, 2022). "In contrast to our previous findings in a TCGA pan-cancer cohort, patients with melanoma in the CCND1 High Amplification group in the present study showed downregulation of many genes associated with angiogenesis (HIF1A, VEGFs, VEGFRs, FGFs, and FGFRs)." (PMID 35844619, 2022). "Our signaling pathway analysis provided novel insights into therapies based on the oxidative metabolism and lipid metabolism activity in melanoma with CCND1 amplification." (PMID 35844619, 2022). "We also established a murine model of melanoma harboring CCND1 amplification and utilized RNA-seq to verify the findings from human tissue samples." (PMID 35844619, 2022). "Consistent with the in vivo findings, CQ and TRA inhibited melanoma cell proliferation in vitro, which was correlated by decreased cyclin D1 expression." (PMID 35847840, 2022). "Our objective was to evaluate the prognostic and clinicopathological significance of cyclin D1 (CD1) overexpression/CCND1 amplification in melanomas." (PMID 33804108, 2021). "The canonical CCND1/cyclin D1 general role—i.e., sustaining cell proliferation—has also been also shown in in vitro and in vivo recent studies in melanoma." (PMID 33804108, 2021). "Cyclin D1 protein expression level correlated positively with CCND1 copy number in acral melanomas with high-level CCND1 copy number increase (P = 0.038)." (PMID 34225728, 2021). "The aim of this study was to evaluate the consistency of CCND1 copy number increase with cyclin D1 protein expression in acral melanomas, and to assess the potential role of cyclin D1 IHC serving as a preliminary screening method for CCND1 FISH." (PMID 34225728, 2021). "In conclusion, CCND1/cyclin D1 upregulation is a common molecular oncogenic alteration in melanomas that probably favors the growth and expansion of the primary tumor." (PMID 33804108, 2021). "In detail, upon treatment with CDK4/6 inhibitors, melanoma cells increase the levels of cyclin D1, which is a master regulator of cell cycle progression." (PMID 34071228, 2021). "Poor response to toripalimab, a humanized IgG4 monoclonal antibody (mAb) against PD-1, correlated with CCND1 amplification in melanomas." (PMID 33923996, 2021). "The frequent CCND1/cyclin D1 upregulation in melanomas has stimulated the research of cyclin D1 inhibitors as a therapeutic tool." (PMID 33804108, 2021).